CCNB2 (cyclin B2)
Description:
Essential for the control of the cell cycle at the G2/M (mitosis) transition.
Synonyms: HsT17299
Tractability: Small molecule: a high-quality ligand is known; it belongs to a druggable protein family. PROTAC: ubiquitination databases record sites on it.
Target class: Other cytosolic protein
Gene: Protein-coding gene on chromosome 15 (59,105,078 to 59,125,045, forward strand). Ensembl gene ENSG00000157456.
Subcellular location (Human Protein Atlas): Cytosol; Golgi apparatus
Pathways (Reactome):
Cell Cycle: Activation of NIMA Kinases NEK9, NEK6, NEK7; Condensation of Prometaphase Chromosomes; Cyclin A/B1/B2 associated events during G2/M transition; G2/M DNA replication checkpoint; Golgi Cisternae Pericentriolar Stack Reorganization; Initiation of Nuclear Envelope (NE) Reformation; Nuclear Pore Complex (NPC) Disassembly; Polo-like kinase mediated events; Regulation of PLK1 Activity at G2/M Transition; Resolution of Sister Chromatid Cohesion; The role of GTSE1 in G2/M progression after G2 checkpoint
Gene Ontology:
Molecular function: cadherin binding; protein binding; cyclin-dependent protein serine/threonine kinase regulator activity
Biological process: mitotic cell cycle phase transition
Cellular component: centrosome; cytosol; Golgi apparatus; microtubule cytoskeleton; cyclin-dependent protein kinase holoenzyme complex; microtubule organizing center; cytoplasm; membrane
Genetic constraint (gnomAD): Loss-of-function variants: 35 observed, 45.82 expected, observed/expected ratio (o/e) 0.76, 90% interval 0.58 to 1.01. The upper end of that interval is the gene's LOEUF score, 1.01, which puts it in group 4 of 6, group 1 being the genes least tolerant of losing a copy. Missense variants: 445 observed, 456.17 expected, observed/expected ratio (o/e) 0.98, 90% interval 0.9 to 1.05. Synonymous variants: 163 observed, 160.44 expected, observed/expected ratio (o/e) 1.02, 90% interval 0.89 to 1.16.
Homologues: Orthologues: chimpanzee CCNB2 (99% identical), macaque CCNB2 (98% identical), rabbit CCNB2 (95% identical), dog CCNB2 (93% identical), pig CCNB2 (92% identical), guinea pig CCNB2 (92% identical), rat Ccnb2 (90% identical), mouse Ccnb2 (89% identical), rat Ccnb2-ps2 (84% identical), tropical clawed frog ccnb2 (56% identical), zebrafish ccnb2 (54% identical), Drosophila melanogaster CycB (39% identical), and 3 more. Paralogues in human: CCNB1 (55% identical), CCNA2 (30% identical), CCNB3 (29% identical), CCNA1 (28% identical), CCNF (23% identical), CCNE1 (22% identical), CCNE2 (22% identical), CCNO (19% identical), CCND3 (18% identical), CCNJ (18% identical), CCND2 (17% identical), CCNP (16% identical), and 6 more.
Diseases named in the same sentence as CCNB2 in open-access papers:
CCNB2 is named in the same sentence as 110 diseases in open-access papers, as found by Europe PMC text mining. Sharing a sentence is not in itself a finding about the gene and the disease. The quoted sentences say what the papers report.
breast carcinoma (43 papers, 2012 to 2025). "Aberrant expression of CCNB2 has been observed in various cancer types, including lung, bladder, and breast cancers 15, and elevated CCNB2 expression is associated with unfavorable prognosis in hepatocellular carcinoma (HCC) patients." (PMID 41049007, 2025). "Our study revealed strong positive correlations between KPNA2 and FOXM1, CCNB1, and CCNB2 expression, with a significant association with the G2/M checkpoint pathway in breast cancer patients." (PMID 40002266, 2025). "CCNB2, a cyclin B family member, is crucial for cell proliferation and tumor advancement, especially in breast cancer and HCC associated with chronic HBV infection." (PMID 38895552, 2024). "In line with CCNA2, CCNB2 increased the risk of multiple cancer prognoses such as such as adrenocortical carcinoma, lung cancer, breast cancer, and colorectal adenocarcinoma." (PMID 33879165, 2021). "For example, elevated cytoplasmic CCNB2 protein levels are strongly associated with short-term disease-specific survival of breast cancer patients." (PMID 30822312, 2019). "Cyclin B2, another regulator of cell division cycle, is commonly overexpressed in breast cancer and is associated with increased invasion and metastasis." (PMID 30038716, 2018). "In summary, we report here that CCNB2 expression represents a threshold that can stratify breast cancer patients in a high risk group associated with an increased probability of mortality when compared to 8-year survivors." (PMID 23282137, 2013). "Elevated cytoplasmic CCNB2 protein levels were strongly associated with short-term disease-specific survival of breast cancer patients (≤ 8 years; P<0.001) and with histological tumor type (P= 0.04)." (PMID 23282137, 2013). "Additionally, CCNB2 has been linked to metastasis in nasopharyngeal cancer, breast cancer, and non-small-cell lung cancer; PLK1 in pancreatic cancer and melanoma; and CCNB1 in esophageal cancer." (PMID 40076867, 2025). "Moreover, CENPL was detected as one of the novel hub genes and served as a prognostic marker candidate in breast cancer, and high expression of CCNB2 in breast carcinoma showed an association with disadvantageous clinical outcomes." (PMID 36077657, 2022). "Results of this study demonstrated that PBMCs are affected by BC cells and CCNB2 may be of value asa diagnostic biomarker for breast cancer." (PMID 34455715, 2021). "Moreover, our study additionally detected a significant correlation between the expression of the ASPM and CCNB2, and the elevated cytoplasmic CCNB2 protein levels were confirmed to be strongly associated with the short-term disease-specific survival of breast cancer patients." (PMID 25961039, 2015). "CCNB1 and CCNB2 are frequently overexpressed in breast cancer, especially in the HER2-positive subtype." (PMID 41009526, 2025). "The FOXM1 directly binds to and regulates CCNB1/CCNB2 promoters for breast cancer cell cycle progression, while KPNA2 modulates this process through its effects on FOXM1 nuclear transport and retention." (PMID 40002266, 2025). "TNXIP expression was also strongly impaired upon SAM stimulation in all tested breast cancer cell lines, as were Cyclin B2 levels." (PMID 40443279, 2025). "Recent research has recognized CCNB2 as a promising noninvasive biomarker for breast cancer in peripheral blood mononuclear cells." (PMID 38895552, 2024). "The aberrant expression of AURKA, BUB1B, CCNA2, CCNB2, and PBK resulted in a poorer survival rate of breast cancer patients in the high-risk group having a survival rate of less than 2 years." (PMID 36980449, 2023). "CCNB2 is also correlated with cancer progression and inferior prognosis in breast cancer, hepatocellular carcinoma and NSCLC." (PMID 37007961, 2023). "The overexpression and oncogenic role of the CCNB2 gene was responsible for the metastasis of breast cancer." (PMID 36980449, 2023).
breast carcinoma (continued). "It has been reported that CCNB2 is highly expressed in tumour tissues, such as breast cancer, adrenal cortical carcinoma, colorectal adenocarcinoma, and pituitary adenoma." (PMID 35037540, 2022). "Previous studies have reported that CCNB2 is overexpressed in bladder carcinoma, breast carcinoma and lung adenocarcinoma." (PMID 35349480, 2022). "In the meantime, the knockdown of CCNB2 blocked G2/M transition in breast cancer cell cycle and increased the number of apoptotic cells." (PMID 36568377, 2022). "Though there are wide effects of CCNB2 on cancer progression, its potential role in breast cancer is still unclear." (PMID 34354775, 2021). "Poorly differentiated breast cancer tumors are characterized by specific set of over-expressed genes (e.g., UBE2C, CCNB2, CDK1, KIF2C, NDC80, and CCNB2) and are associated with more aggressive tumors and lower survival." (PMID 34300003, 2021). "We investigated the expression levels of CCNB2 in human breast cancer tissues according to TCGA database." (PMID 34354775, 2021). "CCNB2 was abnormally expressed in several types of cancers, such as lung cancer, bladder cancer, and breast cancer." (PMID 34354775, 2021). "As an important component in cell cycle regulation, CCNB2 seems to functions as the oncogene and independent prognostic factor for survival in patients with breast cancer." (PMID 33083112, 2020). "Overexpression of CCNB2 has been revealed in cancers such as breast cancer and lung cancer, and it has been reported as a poor prognostic factor." (PMID 32287321, 2020). "As a result, there were nearly 2.1% (CDC20, CDK1), 1.2% (RRM2), 0.9% (BUB1B), 0.8% (CCNA2), 0.7% (CCNB2) of breast cancer samples included in cBioPortal had genetic changes." (PMID 33083112, 2020). "By using the TCGA breast cancer dataset, two genes including CCNA2 and CCNB2 were identified to be associated with the PTTG1." (PMID 32272902, 2020). "In this study, we identified 283 overlapping DEGs (105 up- and 178 down-regulated) and six hub genes (RRM2, CDC20, CCNB2, BUB1B, CDK1, CCNA2) associated with breast cancer tumorigenesis and progression based on multiple datasets." (PMID 33083112, 2020). "Many evidences suggested that CCNB2 expression was increased in a variety of human cancers, such as non-small cell lung cancer, breast carcinoma, gastric cancer, colorectal adenocarcinoma, pituitary adenoma and adrenocortical carcinoma." (PMID 30822312, 2019). "CCNB2 overexpression is negatively correlated with the prognosis of breast cancer patients and is an independent prognostic marker." (PMID 30995921, 2019). "Our results indicated that CCNB2 was upregulated in breast cancer tissues compared to normal tissues, and that its expression was significantly associated with molecular subtypes of breast cancer and tumor stages." (PMID 30254986, 2018). "CCNB2 expression level was reported to be an independent prognostic factor for the disease specific survival of breast cancer." (PMID 30254986, 2018). "Among those five E2F targets correlated with malignant transition, Cdk1 and Plk1 were well studied in breast cancer, but much less so for Ccnb2, Aurkb, and Spag5 (7, 10, and 3 reports, respectively)." (PMID 28212608, 2017). "Multivariate Cox regression analysis specified that CCNB2 protein expression is an independent prognostic marker of DSS in breast cancer." (PMID 23282137, 2013). "In estrogen dependent breast cancer cells, estrogen was shown to increase the expression of cyclin B2 protein and promote cell proliferation." (PMID 23320178, 2012). "Research has shown that CCNB2 is often increased in HBV‐associated HCC and breast cancer, as well as in other human cancers such as lung and liver cancer, and its dysregulation may result in uncontrolled cell proliferation, promoting tumor formation." (PMID 38895552, 2024). "Knockdown of CCNB2 mRNA could inhibit cell proliferation, reduce breast cancer cell migration, block the G2/M cell cycle transition, and increase cell apoptosis." (PMID 36439516, 2022).
breast carcinoma (continued). "CCNB2 functions as an oncogene and could serve as a potential biomarker of an unfavorable prognosis over short-term follow-up in breast cancer." (PMID 33937050, 2021). "In the present study, we found that AME can cause S-phase arrest of breast cancer cells, downregulate the expression of CDC20, AURKB, PLK1, CCNB2, and TOP2A, and upregulate the expression of GADD45A, eventually inhibiting the proliferation of breast cancer cells." (PMID 31275405, 2019). "In addition, 5 hub genes, CCNB2, FBXO5, KIF4A, MCM10, and TPX2 were identified and validated to be associated with the progression and worse prognosis of breast cancer." (PMID 30254986, 2018). "Furthermore, through the K-M survival analysis in TCGA database, we found that the expression of CCNB2 was obviously correlated with the disease-free survival rates of 2 sets of patients with breast cancer collected in different times (n = 803 and n = 963, respectively)." (PMID 34354775, 2021). "Notably, we identified that CCNA2 and CCNB2 were target genes of PTTG1 in breast cancer." (PMID 32272902, 2020). "Moreover, our data suggests that CCNB2 is a potential independent prognostic factor and may be useful in conjunction with other clinicopathological features in breast cancer." (PMID 23282137, 2013). "Thus, the accuracy in patient prognosis may be improved by measuring CCNB2 expression in cases of breast cancer." (PMID 23282137, 2013). "AURKA, BUB1B, CCNA2, CCNB2, and PBK, and these hub genes obtained were found to be upregulated (based on log2fold change value) in breast cancer." (PMID 36980449, 2023). "Elevated expression of the five hub genes AURKA, BUB1B, CCNA2, CCNB2, and PBK are related to poor OS in breast cancer patients." (PMID 36980449, 2023). "The five potential prognostic biomarkers, i.e., Aurora Kinase A (AURKA), BUB1 Mitotic checkpoint serine/threonine kinase B (BUB1B), Cyclin A2 (CCNA2), Cyclin B2 (CCNB2), and PDZ binding kinase (PBK) were upregulated in breast cancer." (PMID 36980449, 2023). "We found that eight cyclins (CCNA2, CCNB1, CCNB2, CCND2, CCNE1, CCNE2, CCNF, CCNO) were differentially expressed between breast cancer and normal tissue samples, with the cut-off criterion of log2(fold change) >1, p < 0.05." (PMID 33791304, 2021). "In the current study, we obtained 283 overlapping DEGs and six hub genes (RRM2, CDC20, CCNB2, BUB1B, CDK1, and CCNA2) related to the occurrence and development of breast cancer via comprehensive bioinformatics analysis." (PMID 33083112, 2020). "In this study we evaluate the potential MGMT’s role in control of therapeutic, clinically relevant, cell cycle regulators involved in breast cancer oncogenesis (CDC2, TOP2A, AURKB, CDC20, KIF20A, Cyclin A2, Cyclin B2, Cyclin D1)." (PMID 30038716, 2018). "We show that O6-benzylguanine (BG), an MGMT inhibitor decreases CDC2, CDC20, TOP2A, AURKB, KIF20A, cyclin B2, A2, D1, ERα and survivin and induces c-PARP and p21 and sensitizes ER positive breast cancer to temozolomide (TMZ)." (PMID 30038716, 2018). "Furthermore, the predictive power for CCNB2 protein expression was higher together with the analyzed clinicopathological parameters (C-index = 0.795) than with the clinicopathological parameters alone (C-index = 0.698) for predicting breast cancer specific-survival within 8-years follow-up." (PMID 23282137, 2013). "The purpose of the present study was to investigate the prognostic value of the candidate biomarkers CCNB2, ASPM, CDCA7, KIAA0101, and SLC27A2 in breast cancer." (PMID 23282137, 2013). "Here, we present a validation of the prognostic role of five selected candidate biomarkers (CCNB2, ASPM, KIAA0101, CDCA7, and SLC27A2) included in these gene signatures using an independent breast cancer cohort." (PMID 23282137, 2013).
breast carcinoma (continued). "Some studies have reported the role of CCNB1, CCNB2, PTTG1, RACGAP1, and UBE2C in cell cycle regulation, aggressive tumor behavior, a poor prognosis, resistance to therapy, and cancer stem cell regulation in breast cancer." (PMID 41009526, 2025). "Relying on the TIMER 2.0 database, we found that CCNB2 was overexpressed in most tumor tissues, such as bladder cancer (BLCA), breast cancer (BRCA), cervical cancer (CESC), esophageal cancer (ESCA), prostate cancer (PRAD) (p < 0.05), and clear cell renal cell carcinoma (ccRCC) (p < 0.001)." (PMID 38300330, 2024). "CCNB2 overexpression stimulates proliferation in vitro and in vivo in three negative breast cancer cells." (PMID 35456460, 2022). "Nevertheless, whether these drugs could exert therapeutic effects on breast cancer by inhibiting the over-expression of RRM2, CDK1 and CCNA2, or whether CCNB2, BUB1B and CDC20 are promising therapeutic targets still need to be supported by further research." (PMID 33083112, 2020). "Thus, elevated levels of CCNB2 may reflect a functional correlation with ASPM overexpression, which could play a role in the progression of breast carcinoma." (PMID 23282137, 2013). "There were negative expression correlations of hsa-let-7a-5p-CCNB2, hsa-let-7c-5p-CCNB2, hsa-let-7a-5p-AURKB, hsa-miR-30a-5p-CDC20, hsa-miR-30a-5p-MYBL2, hsa-miR-29c-3p-OIP5, hsa-miR-10b-5p-CHAF1B, hsa-miR-195-5p-CCNE1, and hsa-miR-497-5p-CCNE1 in ERα positive breast cancer." (PMID 32500028, 2020).